BRAF (B-Raf proto-oncogene, serine/threonine kinase)
Diseases named in the same sentence as BRAF in open-access papers (continued):
Sharing a sentence is not in itself a finding about the gene and the disease.
melanoma (continued). "The recent advances in genomics have proved to be linked to prognosis and response to therapy, for instance BRAF inhibitors have changed the landscape of BRAF V600 E mutant melanomas, and ALK inhibitors have dramatically changed the outcome of EML4-ALK mutant lung cancer patients." (PMID 25859559, 2015). "Therefore, the effects of fisetin on short- and long-term growth of BRAF-mutated A375, SK-MEL-28 and RPMI-7951 melanoma cells were determined by an MTT and colony formation assays." (PMID 26299806, 2015). "We defined “pan-negative” samples as those melanomas harboring none of the well-known, specific, and recurrent mutations in the genes BRAF, NRAS, KIT, GNAQ, or GNA11, which are commonly mutated in melanoma." (PMID 25537510, 2015). "In the randomized phase 2 study comparing nivolumab plus ipilimumab with ipilimumab alone in patients with BRAF wild-type melanoma, ORR was 61 % with combination therapy compared to 11 % with monotherapy, with complete responses seen in 22 and 0 % of patients, respectively." (PMID 26518223, 2015). "The US Food and Drug Administration (FDA) has approved drugs for BRAF mutant melanoma including the BRAF inhibitors vemurafenib (August 2011) and dabrafenib (May 2013) as well as the MEK inhibitor trametinib (May 2013)." (PMID 26334521, 2015). "Therefore, our study demonstrates that the fully automated IHC is a reliable tool to determine BRAF mutation status in CRC, PTC and melanoma and can be used for routine clinical screen." (PMID 25784606, 2015). "On the other hand, ERβ agonists will not reduce the growth of melanoma cells harboring the BRAF (V600E) mutation, which is associated with the overactivation of the MEK/ERK signaling pathway." (PMID 26225426, 2015). "Moreover, SCH772984, as a selective and potent ERK1/2 inhibitor, has been recently shown to induce apoptosis and cell cycle arrest in BRAF-mutant or non-BRAF-mutant melanoma." (PMID 25742792, 2015). "Actually, NRAS and BRAF mutations are very frequently found in melanoma tumors; in particular, BLM cells are NRAS-mutant (a mutation present in about 30% of patients), while both A375 and WM1552 cells harbor the BRAF V600E mutation (the predominant BRAF mutation, occurring in about 50% of cases)." (PMID 26225426, 2015). "Although response rates within genetically-selected subpopulations of solid tumor cancer patients can be high, such as 60–80% among BRAFV600E mutant melanoma patients receiving the BRAF inhibitor vemurafenib, few patients achieve single-agent complete responses." (PMID 26461489, 2015). "Moreover, the intracellular accumulation of a splicing variant of the BRAF-mutant mRNA has been described in a subset of BRAF-inhibitor-resistant melanoma cells." (PMID 26322273, 2015). "Vemurafenib, a potent inhibitor of (V600E) BRAF in melanoma cells, is currently in clinical use." (PMID 26697165, 2015). "Interestingly, BRAF mutant/PTEN-null melanoma cells showed much higher sensitivity to ZA treatment as PTEN wild-type BRAF mutant cells." (PMID 25646931, 2015). "We have shown that the combination of the two drugs together significantly improved the therapeutic efficacy when compared to ADI-PEG20 alone or cisplatin alone in 4 melanoma cell lines, regardless of their BRAF mutation." (PMID 25749046, 2015). "These BRAF inhibitors have revolutionized therapy for patients with BRAF V600–mutant advanced melanoma and demonstrated promising results in patients with other BRAF mutation–harboring diseases, including histiocytosis, hairy cell leukemia, non–small cell lung cancer, and biliary cancer." (PMID 26330075, 2015). "There is limited published data on the molecular alterations associated with MBM, although in general, debate in the literature exists as to whether BRAF and/or NRAS mutated melanomas are associated with worse survival outcomes compared to WT tumors." (PMID 26597176, 2015).
melanoma (continued). "More recently, in melanomas previously considered pan-negative for common driver mutations, we identified non-V600 BRAF mutations at codons L597 and K601 and BRAF fusions." (PMID 26084293, 2015). "In addition to BRAF-specific inhibition with vemurafenib and dabrafenib, the MEK1/2 inhibitor trametinib is also approved for the treatment of metastatic or unresectable BRAF V600-mutant melanoma." (PMID 26084293, 2015). "In trials of patients with melanoma being treated with checkpoint inhibitors, responses have been observed in patients with and without BRAF mutations, brain metastases, or prior treatment." (PMID 25682878, 2015). "Six previously reported independent melanoma biomarkers, including BRAF, MMP2." (PMID 25784655, 2015). "To address whether BAY 87-2243-mediated complex I inhibition is efficient at reducing melanoma tumor growth in vivo, we tested the inhibitor in four BRAF mutant melanoma xenograft models using G-361, SK-MEL-28, A-375, and LOX-IMVI cancer cells." (PMID 26500770, 2015). "Moreover, their results suggested that melanoma progression is promoted by SOCE through CaMKII/Raf-1/ERK signaling pathway, independently of BRAF mutations." (PMID 25710007, 2015). "Importantly, this link appears to be maintained in melanoma where oncogenic BRAF or NRAS hyperactivates the MAPK pathway." (PMID 25818589, 2015). "Furthermore, stability of anti-apoptotic protein Mcl-1 in melanoma cells is regulated by ERK1/2, and enhanced expression of this protein in melanoma cells has demonstrated resistance against BRAF inhibitor-induced apoptosis." (PMID 26299806, 2015). "Indeed, MITF is essential for the maintenance of oncogenic BRAF‐driven melanoma in vivo, and the level of MAPK pathway activation appears to be critical for MITF abundance and function in melanoma cells." (PMID 25818589, 2015). "Although an important step in pancreatic cancer, as in EGFR- or ALK-mutant lung cancer or BRAF-mutant melanoma might include investigation of matched targeted monotherapy, many pancreatic tumors likely contain more than one aberration." (PMID 25714017, 2015). "In addition, the side-effect and toxicity profile (19% of cutaneous squamous cell carcinoma in BRAF inhibitor arm vs. 7% in the combination arm in melanoma patients) favors the combination therapy." (PMID 25706985, 2015). "Overall, 418 previously untreated patients with BRAF-positive melanoma took part in the study." (PMID 26171394, 2015). "No discordance concerning BRAF mutational status was observed among the 46 patients with at least two distinct melanoma samples, and the median BRAF-M% variation was 2.5 %." (PMID 26141748, 2015). "Expression of oncogenic BRAF(V600E) was clastogenic in two human melanoma cell lines." (PMID 26091525, 2015). "Here, we selected a panel of low-passage BRAF-mutant melanoma cell lines that were established and maintained at 5% oxygen tension to mimic physiological oxygen concentrations and were sensitive to the MEK inhibitor selumetinib and the BRAF inhibitor vemurafenib." (PMID 26137449, 2015). "BRAF has become an important therapeutic target for patients with advanced malignant melanoma." (PMID 26705496, 2015). "Our data suggest that IHC for BRAF could serve as a useful prognostic marker in the early stage of melanoma as well." (PMID 25784655, 2015). "Thus, treatment with an mTOR inhibitor renders angiosarcomas as sensitive to MEK inhibition as melanomas having mutant BRAF, and it renders MEK inhibitor-resistant cells sensitive to MEK inhibition." (PMID 25955301, 2015). "Furthermore, malignant melanoma cells that survive and proliferate after treatment with mutant BRAF (V600E) inhibitor tend to exhibit relative dependence on mitochondrial metabolism." (PMID 26445347, 2015).
melanoma (continued). "Interestingly, we observed that BAY 87-2243 displayed increased anti-tumor efficacy compared to single agent treatment when combined with the small molecule mutant BRAF inhibitor vemurafenib in nude mice bearing BRAF mutant melanoma xenografts." (PMID 26500770, 2015). "Particularly, in melanomas the BRAF complex mutations were 20% of the total BRAF detected mutations (6/30: 1 p.V600E2 and 5 pV600K), revealing that such events are not rare and they must be taken into account when performing BRAF testing." (PMID 26435479, 2015). "The BRAF/NRAS wild-type melanomas, i.e. samples negative for mutations in both BRAF and NRAS, more often had genetic alterations in KIT or NF1 (P < 0.001, Fisher's exact test)." (PMID 25909218, 2015). "A panel of nine early passage BRAF-mutant metastatic melanoma cell lines that were developed and maintained at 5% oxygen tension to mimic physiological oxygen levels in the tumor microenvironment was selected that displayed a range of sensitivities to selumetinib and vemurafenib." (PMID 26137449, 2015). "Similar to the adaptation of BRAF-mutant melanoma cells to BRAF inhibition, resistance to MEK inhibitors could involve multiple pathways." (PMID 24743024, 2014). "Importantly, analysis of human melanoma biopsies before and during BRAF inhibitor treatment also showed downregulation of VEGF consistent with the preclinical murine model." (PMID 24743024, 2014). "Interestingly, these investigators had also observed that EGFR expression in BRAF mutant melanoma cells was surprisingly detrimental to their proliferative capacity, and was only tolerated in the context of BRAF inhibition." (PMID 25031620, 2014). "Inhibition of MEK has been explored in clinical trials for melanoma patients with mutant BRAF." (PMID 24743024, 2014). "Therefore, we designed an integrated strategy using (phospho)proteomic and functional genomic platforms to identify drug targets whose inhibition sensitizes melanoma cells to BRAF inhibition." (PMID 25538140, 2014). "Furthermore, in melanoma cells that persist after BRAF inhibition, Rnd3 restoration decreased cell invasion." (PMID 25538140, 2014). "This pattern was mirrored in melanoma tissue samples from patients treated with BRAF inhibitors, vemurafenib and dabrafenib, indicating that de-repression of TRIM16 expression in melanoma cells is a novel therapeutic approach and provides new insights into the mechanism of action of BRAF inhibitors." (PMID 25333256, 2014). "In addition, inhibition of MEK (the only known phosphorylation substrate of BRAF) is considered to be a valid therapeutic intervention for both BRAF- and NRAS-mutated melanoma." (PMID 24743024, 2014). "Agents approved to treat these subpopulations include the BRAF inhibitors vemurafenib and dabrafenib, and the MEK inhibitor trametinib, which are indicated for adult patients with BRAFV600 mutation-positive advanced melanoma." (PMID 24885479, 2014). "This supports the hypothesis that targeting inhibitory immune interactions may be critical in augmenting responses to BRAF-targeted therapy in patients with melanoma." (PMID 24743024, 2014). "Finally we demonstrate a striking association between the expression of THBS1 and drug resistance, not only to cytotoxic drugs, but also in melanoma cells resistant to BRAF inhibition." (PMID 25051363, 2014). "Using BRAF and NRAS mutation analysis, it could be proven that both lesions were melanoma metastases instead of SFT." (PMID 25593912, 2014). "In the syngeneic SM1 mouse model of BRAFV600E melanoma, an improved antitumor activity was observed after combining BRAF inhibition with adoptively transferred T cells, leading to increased in vivo cytotoxic activity and intratumoral cytokine secretion by the transferred T cells." (PMID 25610709, 2014).
melanoma (continued). "Recent studies also implicate that XPO1 inhibitors may synergize with BRAF inhibition in human melanoma cell lines, supporting the concept that nuclear export inhibition may play a role as a therapeutic strategy for this disease." (PMID 25057921, 2014). "Additionally, ABT-737 in combination with the BRAF inhibitor PLX4720 showed augmentation of apoptosis in BRAF mutant melanoma cell lines that was BIM dependent and mediated through an enhancement of the BIM:MCL-1 interaction." (PMID 24983357, 2014). "Providing further support of this strategy, preclinical studies of ABT-737 in combination with a MEK inhibitor led to enhanced lethality, in vitro and in vivo utilizing BRAF-mutant melanoma cell lines and xenografts respectively, compared to either agent alone." (PMID 24983357, 2014). "To evaluate whether induction of TRIM16 expression was necessary for vemurafenib effects on melanoma cell viability we silenced TRIM16 gene expression using two TRIM16-specific siRNA's and treated BRAF-mutant A375 melanoma cells with vemurafenib." (PMID 25333256, 2014). "Interestingly, IPA3 specific PAK inhibitor is able to inhibit the proliferation of melanoma and CRC cells with mutations at KRAS or NRAS better, than those containing mutations at BRAF." (PMID 25361007, 2014). "In this context it is important to mention that wild type BRAF melanoma cells that had been selected for resistance to light activated DTIC in vitro exhibited increased tumour growth in vivo, a phenotype that correlates well with enhanced DNA synthesis activity." (PMID 24941944, 2014). "To address the potential influence of the genetic background on the response of melanoma cells to chemotherapeutic agents, we tested three different classes of DNA damaging agents: carmustine, cisplatin and DTIC in 9 NRAS mutant and 9 BRAF mutant melanoma cell lines (mutNRAS and mutBRAF cells)." (PMID 24941944, 2014). "Furthermore, we evaluated the cytotoxic effects of combining a BH3-mimetic, navitoclax, with a BRAF inhibitor in vitro and in vivo in melanoma cell lines." (PMID 24983357, 2014). "Among BRAF mutation-negative melanomas, 6 N-RAS mutations (four Q61R, one Q61K, and one Q61L) and 3 KIT mutations (N822K) were found." (PMID 24591764, 2014). "This correlation was also found in a meta-analysis which included 36 prior studies and additionally described the localization of the primary melanoma in non-chronically sun-damaged skin as a factor associated with a high rate of BRAF mutations." (PMID 24475086, 2014). "Moreover, downregulation of Noxa has been recently reported to counteract apoptosis induction by BRAF inhibitors in mutant BRAF melanoma cells." (PMID 25365078, 2014). "This indicates that melanomas with a higher dependence on glycolysis might be more sensitive to mutant BRAF inhibition." (PMID 24743024, 2014). "We therefore asked whether miR-146a expression is upregulated in melanoma cell lines containing mutant BRAF or NRAS." (PMID 24550252, 2014). "Consistent with our finding that MEK/ERK signaling also enhances activation of CREB, a recent study has demonstrated by analysis of biopsies from BRAFV600E melanoma patients that activation of CREB was supressed by inhibition of mutant BRAF or MEK but restored in relapsing melanomas." (PMID 25365078, 2014). "Oncogenic mutations in BRAF and NRAS occur in 70% of melanomas." (PMID 24550252, 2014). "Mutations in the c-KIT gene, along with BRAF mutations, in part, considered to be involved in the mechanism of development and progression of melanoma, have been identified in mucosal melanoma, which not only implicates BRAF, but also c-KIT, as a promising molecular target." (PMID 25120707, 2014). "Mechanistic studies have provided insights into the development of resistance through two major mechanisms: new mutations in the RAF-MAPK pathway itself and changes in other oncogenic pathways, mainly RAS and PI3K, that relieve melanoma cells from reliance on BRAF signaling." (PMID 24743024, 2014).
melanoma (continued). "BRAF-mutant melanomas may develop multiple mechanisms of resistance simultaneously, even within a single cell line, and some of them may drive resistance to multiple MAPK inhibitors." (PMID 25344914, 2014). "Furthermore, this paper also gives mutation frequencies of BRAF (25%) and NRAS (10%) that are quite different from most studies in the melanoma field." (PMID 25593912, 2014). "In 2011, vemurafenib was approved for the treatment of BRAF-mutant melanoma patients." (PMID 25277503, 2014). "Building on their previous observation of intrinsic resistance of BRAF mutant colorectal cancers to epidermal growth factor receptor (EGFR) activation, these investigators explored a potential role for EGFR in acquired resistance to BRAF inhibition in BRAF mutant melanoma." (PMID 25031620, 2014). "After removal of trametinib one can hypothesize that the melanoma cells would switch back to depend on BRAF independent MAPK pathway signaling, which naturally raises the thought of combining all three inhibitors; dabrafenib, trametinib and AKTi." (PMID 24735930, 2014). "Moreover in melanoma cell lines, the activation of ATF6 is also modulated by MEK/ERK signaling and thus conditioned by BRAF mutation status." (PMID 25437182, 2014). "Recent studies show that EGFR expression occurs in a significant percentage of BRAF resistant melanomas, and receptor activation, though disadvantageous under normal conditions, becomes beneficial when the MAPK pathway is blocked in BRAFV600E positive melanomas." (PMID 24970815, 2014). "In vitro treatments with an EGFR inhibitor in combination with a BRAF inhibitor, or monotherapy with dasatinib, appeared to overcome this resistance and could deliver therapeutic efficacy in drug-resistant BRAF-mutant melanoma patients." (PMID 24743024, 2014). "In the clinical setting, BRAF mutations are routinely screened but when BRAF mutation is not detected, melanomas should be screened for N-RAS, KIT, and GNAQ mutations." (PMID 24591764, 2014). "Melanomas with BRAF mutations other than V600 have not been specifically targeted in clinical trials." (PMID 24743024, 2014). "These alterations in other pathways, such as the PI3K pathway, may partially explain the resistance of BRAF-mutant melanoma to RAF inhibitors." (PMID 25393105, 2014). "We reasoned that the lack of BRAF mutation in early melanoma in situ prevents these tumor cells to go into senescence, thus maintaining malignant potential." (PMID 25526463, 2014). "Furthermore, SINE compounds exhibited synergistic activity with BRAF inhibitors PLX4720 and PLX4032 against BRAF mutant melanoma." (PMID 24503695, 2014). "This treatment strategy is also being explored in patients with BRAF-mutant melanoma and may prove effective in circumventing acquired drug resistance." (PMID 25594040, 2014). "In support of this notion, while BRAF mutations are present in both nevi and melanoma sections of contiguous nevi-melanoma biopsies, activation of PI3K (through loss of PTEN expression or activation of AKT3) was detected in the melanoma portions only." (PMID 24743024, 2014). "The BRAF-MEK-ERK (MAPK) pathway is a key regulator of melanoma cell invasion." (PMID 24466036, 2014). "Similarly, the role of RTKs and MET has emerged as one of the resistance mechanisms to the BRAF inhibitor (vemurafenib) in melanoma." (PMID 28548075, 2014). "In the current study we analyzed frequency and type of oncogenic mutations in known oncogenes (BRAF, NRAS, and KIT) involved in melanoma development in large contemporary series of MUP patients with long follow-up, and we correlated these outputs with disease clinical features and outcome." (PMID 24866436, 2014). "For example, activating BRAF mutations (e.g. V600E) have been associated with a benefit using vemurafenib in melanomas, but not in colorectal carcinomas due to the activation of EGFR pathway in colon cancer." (PMID 25415047, 2014).